PLK1 (polo like kinase 1)
Diseases named in the same sentence as PLK1 in open-access papers (continued):
Sharing a sentence is not in itself a finding about the gene and the disease.
glioma (continued). "In summary, identified signaling was unique to volasertib mediated anti-tumor response in glioblastoma and provide additional support for the PLK1 inhibition as an adjunct to SOC in glioma and the search for biomarkers that predict its efficacy." (PMID 34680264, 2021). "CCK8 assay, EdU assay and Transwell assay were conducted to detect the effect of circ-ZNF609, miR-1224-3p and PLK1 on proliferation, migration and invasion in glioma cells." (PMID 33976745, 2021). "Materials and methods: Real-time quantitative PCR (qRT-PCR) was applied to measure the expression of circ-ZNF609, miRNA-1224-3p (miR-1224-3p) and Polo-like kinase 1 (PLK1) in glioma tissues and cell lines." (PMID 33976745, 2021). "Next, we co-transfected glioma cells with PLK1 siRNA and miR-1224-3p inhibitor, and examined the expression level of PLK1." (PMID 33976745, 2021). "Then, we conducted in vitro experiments to explore the influence of PLK1 and miR-1224-3p on glioma cell." (PMID 33976745, 2021). "Downregulation of PLK1 protein enhanced the drug-resistance of temozolomide (TMZ) in CD133+ stem-like glioma cell lines, while G2/M arrest was induced significantly." (PMID 32121037, 2020). "lncRNA ENST00000413528 is closely related to the development of glioma via the miR‐593‐5p/PLK1 pathway." (PMID 30924320, 2019). "In glioma tissues, the relative expression of PLK1 protein was positively correlated with lncRNA ENST00000413528 (R2 = 0.4086, P < 0.05)." (PMID 30924320, 2019). "In glioma, Plk1 inhibition has been shown to arrest cells in the mitotic phase of the cell cycle, impair proliferation, migration, and invasion and to induce apoptosis." (PMID 31475119, 2019). "Taken together, our results reveal a regulatory axis of lncRNA ENST00000413528/miR‐593/PLK1 in glioma, to our knowledge, this is the first research project of lncRNA ENST00000413528 expression profile in glioma." (PMID 30924320, 2019). "To further verify the effect of PLK1 on tolerance in glioma stem cells, we inhibited or increased the expression of PLK1 protein in CD133+ U87 stem cells and CD133+ U251 stem cells." (PMID 30133120, 2018). "In conclusion, our results suggest that down‐regulation of PLK1 protein enhanced the inhibition of TMZ on glioma stem cells, suggesting its clinical value to adverse TMZ resistance in glioma treatment." (PMID 30133120, 2018). "Polo-like kinase 1 is overexpressed in human gliomas, and specific inhibitors of these kinases are being investigated as anticancer agents." (PMID 20920292, 2010). "Moreover, we found that TRIM26 phosphorylation levels were correlated with PLK1 activity in a panel of glioma cell lines and confirmed endogenous binding between PLK1 and TRIM26, suggesting that PLK1 is a key kinase that targets TRIM26." (PMID 37872147, 2023). "Moreover, high expression of TRIM26, GPX4 and PLK1 was correlated with poor survival in patients with glioma." (PMID 37872147, 2023). "And the receiver operating characteristic (ROC) curve verified that PLK1 could be an effective factor for predicting WHO grades of glioma." (PMID 36618405, 2022). "Moreover, the expression levels of PLK1 mRNA correlated with the histologic classification of gliomas." (PMID 36618405, 2022). "Therefore, we demonstrated the expression differences and biological roles of PLK1 in normal human astrocyte (HA) cell lines and several glioma cells lines through some experiments, taking glioma as the representative." (PMID 36618405, 2022). "And the ROC curve verified that PLK1 could be an effective factor for predicting pan-glioma in the CGGA-325, CGGA-693, and TCGA datasets." (PMID 36618405, 2022). "In summary, these results suggested that low methylation levels of PLK1 might contribute to its overexpression in pan-cancer, especially in glioma." (PMID 36618405, 2022). "What’s more, we verified that knockdown of PLK1 could increase the expression of the M1 macrophage chemokine CCL5 in glioma cell lines U87 and LN229." (PMID 36618405, 2022).
glioma (continued). "The PLK1 gene in two glioma cell lines was knocked down with siRNA." (PMID 36618405, 2022). "Then, it was confirmed that PLK1 might be related to the tumor immunity of glioma by M1-like macrophages infiltration and polarization assays and intracranial xenograft mouse models." (PMID 36618405, 2022). "Finally, PLK1 methylation analysis and lncRNA-miRNA network revealed the potential mechanism of abnormal PLK1 expression in glioma." (PMID 36618405, 2022). "Furthermore, high methylation levels of PLK1 contributed to poor prognosis and advanced grades in glioma patients." (PMID 36618405, 2022). "PLK1 is always highly expressed in multiple cancers especially in glioma." (PMID 36618405, 2022). "The results of bioinformatics analysis indicated that gene alteration and anti-tumor immunity might be the potential oncogenic mechanisms of PLK1 in pan-cancer, especially glioma." (PMID 36618405, 2022). "However, according to previous research, the mRNA and protein level of PLK1 in glioma tissues is up-regulated." (PMID 36618405, 2022). "It is worth noting that PLK1 affects the TIM of glioma by regulating M1 macrophages infiltration." (PMID 36618405, 2022). "Therefore, we used a number of databases to detect the molecular features of PLK1 gene expression, gene alteration, immune infiltration, cell cycle in pan-cancer, especially glioma." (PMID 36618405, 2022). "In conclusion, our present study suggested that PLK1 may have potential as a diagnosis and prognostic marker as well as immunotherapeutic targets for several malignant tumors, especially glioma." (PMID 36618405, 2022). "Furthermore, PLK1 expression levels correlated with the grades, the histologic classification, and clinical features of gliomas." (PMID 36618405, 2022). "Moreover, high PLK1 mRNA levels were associated with shorter disease specific survival (DSS) and progression free survival (PFI) in pan-glioma and HGG patients in TCGA dataset." (PMID 36618405, 2022). "Cox regression analysis showed that PLK1 was an independent prognostic predictor in glioma." (PMID 36618405, 2022). "Moreover, we confirmed the high expression of PLK1 in glioma tissues by RNA sequencing of 100 glioma tissues." (PMID 36618405, 2022). "Furthermore, in glioma xenograft mouse models, we showed that inhibiting PLK1 blocked tumor proliferation and increased the M1 macrophages infiltration." (PMID 36618405, 2022). "However, the detailed mechanisms surrounding the regulation of PLK1 on glioma immune microenvironment remain undefined." (PMID 36618405, 2022). "In our studies, high PLK1 level was also associated with clinical features such as grade, IDH mutation status, 1p/19q co-deleted status, and methylation status of MGMT promoter in glioma." (PMID 36618405, 2022). "Moreover, analysis of 100 glioma cases collected by our group also showed that PLK1 mRNA level was positively correlated with glioma grade and poorer prognosis, which was consistent with our analysis results in CGGA and TCGA databases." (PMID 36618405, 2022). "In conclusion, our study suggests that circ-ZNF609 might act as an oncogene to promote glioma progression via regulating miR-1224-3p/PLK1 axis." (PMID 33976745, 2021). "Furthermore, we explored the expression level of PLK1 in glioma and found that PLK1 expression was extremely increased in glioma tissues and cell lines." (PMID 33976745, 2021). "In our findings, we suggest that circ-ZNF609 might significantly promote the proliferation, migration and invasion of glioma cells through the miR-1224-3p/PLK1 axis, whose function might involve molecular targets beneficial for diagnosing and treating glioma." (PMID 33976745, 2021). "Additionally, PLK1 has been reported to be upregulated in glioma and can markedly promote cell proliferation and migration 44-46." (PMID 33976745, 2021). "Mechanistically, circ-ZNF609 might promote PLK1 expression by binding to miR-1224-3p, so as to promote glioma growth and metastasis." (PMID 33976745, 2021).
glioma (continued). "Mechanistically, circ-ZNF609 could promote PLK1 expression via binding to miR-1224-3p, circ-ZNF609/miR-1224-3p/PLK1 was shown responsible for circ-ZNF609 promoting glioma growth and metastasis." (PMID 33976745, 2021). "Overall, we concluded that circ-ZNF609 might participate in the progression of glioma through sponging miR-1224-3p to increase the expression level of PLK1." (PMID 33976745, 2021). "We identified that decreased expression level of PLK1 in glioma cells obviously inhibited cell proliferation, migration, and invasion, while co-transfection of PLK1 siRNA and miR-1224-3p inhibitor in glioma cells respectively reversed the inhibition influence of si-PLK1 on glioma cells." (PMID 33976745, 2021). "The therapeutic impact of targeting PLK1 is relatively unknown in paediatric gliomas, with only one study describing the in vitro efficacy of direct PLK1 inhibition in DMGs." (PMID 34944870, 2021). "This suggested that miR-1224-3p may inhibit proliferation, migration and invasion of glioma cells by targeting PLK1." (PMID 33976745, 2021). "Moreover, after transfection of miR-1224-3p mimics and inhibitor in glioma cells, we examined the level of PLK1." (PMID 33976745, 2021). "Moreover, in glioma tissues, the relative expression of PLK1 protein was negatively correlated with miR‐593 (R2 = 0.5228, P < 0.05)." (PMID 30924320, 2019). "The expression of PLK1 in glioma tissues was also examined by immunohistochemistry staining." (PMID 30924320, 2019). "We, thus, hypothesized that lncRNA ENST00000413528 may sponge miR‐593‐5p to regulate PLK1 to exert its effects on glioma cells and designed a series of experiments to verify our hypothesis." (PMID 30924320, 2019). "After the qRT‐PCR verification in glioma tissues and biological informational analysis, we found a possible ceRNA pathway of lncRNA ENST00000413528, which shared a complementary area with miR‐593‐5p, and associated with the target gene PLK1." (PMID 30924320, 2019). "In summary, PLK1, CCNA2, CCNB2, and AURKA were screened as candidate diagnostic marker genes of glioma, and hsa-let-7b-5p could inhibit the invasion and metastasis of glioma cells." (PMID 30995921, 2019). "Interestingly, glioma cases with high PLK1 expression demonstrated a poorer survival compared with those with low PLK1 expression (P = 0.0029)." (PMID 30995921, 2019). "PLK‐1 protein could be mainly cytoplasmic stained in glioma tissues while hardly stained in PTBE tissues." (PMID 30924320, 2019). "What's more, TMZ and PLK1 inhibitor synergize to inhibit glioma growth in vivo." (PMID 30133120, 2018). "Hence, we employed experiments to examine the interaction of PLK1 and TMZ in TMZ‐resistant glioma cells, and found that PLK1 expression was impeded with the increase in TMZ concentration." (PMID 30133120, 2018). "The sensitivity of IDH1 mutant tumors to a PLK1 inhibitor plus TMZ combination may have implications beyond glioma treatment." (PMID 28178660, 2017). "Mutant IDH1 promotes checkpoint adaptation which can be exploited therapeutically with the combination of TMZ and a PLK1 inhibitor, indicating PLK1 inhibitors may be clinically valuable in the treatment of IDH1 mutant gliomas." (PMID 28178660, 2017). "Interestingly, some studies have shown that PLK1 inhibitors could inhibit glioma cell proliferation and glioma progression." (PMID 36618405, 2022). "Moreover, compared with the control group, volasertib can increase the signal of M1 macrophages marker iNOS in the tumor region, which suggested that PLK1 inhibition could increase the M1 macrophages infiltration to glioma TIM." (PMID 36618405, 2022). "Therefore, based on these analysis results, we speculated that PLK1 might promote tumor genesis and development by affecting cell cycle, genetic alterations, and antitumor immune in pan-cancer, especially in glioma." (PMID 36618405, 2022). "In addition, we also conducted a lncRNA-miRNA regulatory network that may regulate the aberrant expression of PLK1 in glioma." (PMID 36618405, 2022).
glioma (continued). "In addition, the enrichment analysis suggested that PLK1 might related to “immune response”, “cell cycle”, “DNA replication”, and “mismatch repair” in glioma." (PMID 36618405, 2022). "Furthermore, qRT-PCR has verified that PLK1 is high expressed in glioma cell lines and tissues." (PMID 36618405, 2022). "In addition, multiple Cox regression revealed grade, IDH mutations, 1p/19q codeletions, promoter methylation of MGMT, and PLK1 mRNA levels might be independent predictors of prognosis of glioma patients." (PMID 36618405, 2022). "Therefore, we investigated the lncRNA-miRNA network that may regulate PLK1 expression in various tumors especially in glioma." (PMID 36618405, 2022). "Therefore, PLK1 is an effective target for the treatment of gliomas." (PMID 30995921, 2019). "Our study suggested that PLK1 inhibitors may be a novel therapies target for glioma treatment." (PMID 30133120, 2018). "We have analyzed the level of Reg-2 and its newly identified targets that encode the cyclins CCND1, CCNE1, CCNE2, CCNB1, CCNA2, and the kinases PLK1 and AURKA in glioma tumors." (PMID 38238463, 2024). "This highlights YBX1’s crucial role as PLK1 inhibition triggers cell death and DNA damage via YBX1 phosphorylation, offering insight into potential glioma treatment mechanisms." (PMID 38255791, 2024). "PLK1 has been shown to be a valid target in MYC-driven cells such as lymphoma, glioma, and medulloblastoma, where onvansertib sensitized tumors to radiotherapy, and pediatric malignancies synergizing with vincristine." (PMID 37183219, 2023). "Collectively, these findings suggest that PLK1 inhibition exhibits potent antitumor activity in vivo, and the combination therapy of PLK1 inhibition and TMZ is an effective strategy for glioma treatment." (PMID 36805592, 2023). "PLK1 mRNA expression strongly correlated with WHO grades, KPS and the recurrence of tumors of patients with gliomas." (PMID 37644431, 2023). "The methylation levels of PLK1 in WHO I gliomas were significantly higher than that in WHO II and WHO IV gliomas." (PMID 36618405, 2022). "Next, we analyzed PLK1 mRNA expression levels in different WHO grades and histologic classifications of gliomas." (PMID 36618405, 2022). "PLK1 protein expression level is high in the logarithmically growing adult (U87 and LNZ308) and pediatric (SJG2 and SF8628) glioma cell lines." (PMID 34058053, 2022). "In the present study, the expression levels of CCAN2, CCNB2, PLK1, and AURKA in glioma were upregulated, and hsa-let-7b-5p binding sites were found in four gene sequences." (PMID 30995921, 2019). "The PLK1 expression showed a significantly and gradually increased tendency from PTBE, low‐grade glioma to high‐grade glioma tissues." (PMID 30924320, 2019). "As reported in pediatric glioma SF188 cells, BI2536, a PLK1 inhibitor, induced apoptosis determined by PARP‐1 cleavage in A172 cells." (PMID 30221846, 2018). "We examined the tolerance of stem cells isolated from glioma cell line U87 and U251 to temozolomide (TMZ) and explored the effect of PLK1 (Polo like kinase 1) protein expression on TMZ sensibility." (PMID 30133120, 2018). "In glioma stem cells, PLK1 interacts with YBX1 and phosphorylates serine residues YBX1–176 and 174, leading to reduced YBX1 levels and inhibition of its nuclear translocation, inducing apoptosis and DNA damage in glioma stem cells." (PMID 40799245, 2025). "Finally, we performed an IHC assay on 83 human glioma samples, and observed that TRIM26 expression was positively correlated with GPX4 and PLK1 protein levels." (PMID 37872147, 2023). "Overall, our results suggested that PLK1 could regulate immune cells infiltration to glioma TIM and might be a potential immune biomarker of glioma." (PMID 36618405, 2022). "Patients in PLK1-high group had poorer prognosis compared to those in PLK1-low group both in chemoradiotherapy and no-chemoradiotherapy glioma patients in CGGA-325 and CGGA-693 datasets." (PMID 36618405, 2022).
glioma (continued). "Therefore, we also analysis the relationship between PLK1 expression and the tumor immune microenvironment (TIM) in pan-cancer, especially in glioma." (PMID 36618405, 2022). "Patients in PLK1-high group had poorer prognosis compared to those in PLK1-low group in both IDH mutated and non-mutated glioma patients in CGGA-325 and CGGA-693 datasets." (PMID 36618405, 2022). "Patients in PLK1-high group had poorer prognosis compared to those in PLK1-low group only in 1p19q non-codeletion glioma patients in CGGA-325, CGGA-693, and TCGA datasets." (PMID 36618405, 2022). "Additionally, the relationship between PLK1 methylation levels and WHO grade of glioma was analyzed across the CGGA database." (PMID 36618405, 2022). "Indeed, we found a close correlation between TRIP13 and Plk1 (r = 0.7016, p < 10−15) in GBM, which provides for the rational development of new targeted therapies for glioma." (PMID 34066132, 2021). "In addition, the PLK1 pathway plays a certain role in the progression of HCC, glioma, and lung adenocarcinoma." (PMID 32104702, 2020). "The results showed that hsa-let-7b-5p could regulate target genes, including cell cycle protein A2 (CCNA2), CCNB2, PLK1, and AURKA, and further affect the progress of glioma." (PMID 30995921, 2019). "In summary, our study proposed the synergistic inhibition effect of PLK1 inhibitor with TMZ on glioblastoma stem‐like cells and suggested the critical role of PLK1 in glioma stem cells progression, providing new treatment strategies for gliomas." (PMID 30133120, 2018). "We also examined whether the combination of PLK1 inhibitor and TMZ displays synergistically anti‐glioma effects in vivo." (PMID 30133120, 2018). "However, the molecular mechanisms of IQGAP3 in relation to the PLK1/PI3K/AKT pathway in glioma have not been explored." (PMID 38560572, 2024). "Results of the TCGA database analysis showed that PLK1 mRNA expression was significantly higher in the GBM tissues than in the normal tissues, and PLK1 had the highest level of expression in patients with World Health Organization (WHO) grade IV glioma and GBM." (PMID 36805592, 2023). "Then, we analyzed the correlation between miR-1224-3p and PLK1 in glioma tissues and a negative relationship between these two molecules was observed in low grade glioma tissues (R2=0.29, p<0.001) and high grade glioma tissues (R2=0.33, p<0.001)." (PMID 33976745, 2021). "Unlike differentiated cells, glioma stem cells responded to moderate Aurora A inhibition with spindle defects, polyploidization and a dramatic increase in cellular senescence, and were selectively sensitive to Aurora A and Plk1 inhibitor treatment." (PMID 24879067, 2014). "Besides, the hypothesis that PLK1 is closely related to genetic alterations, immune, and cell cycle in tumors was also supported by KEGG and GO enrichment analysis of its related genes in glioma." (PMID 36618405, 2022). "Patients in PLK1-high group had poorer prognosis compared to those in PLK1-low group both in MGMT promoter methylated and no-methylated glioma patients in CGGA-325, CGGA-693, and TCGA datasets." (PMID 36618405, 2022). "PLK1 protein could not be detected in peritumoral brain edema (PTBE) tissues; however, it showed an increasing number of positively cytoplasmic stained from WHO‐Grade II to Grade III gliomas." (PMID 30924320, 2019).